RNA5S2 (RNA, 5S ribosomal 2)
Synonyms: RN5S2
Gene: Ribosomal RNA gene on chromosome 1 (228,612,509 to 228,612,627, reverse strand). Ensembl gene ENSG00000201588.
Gene Ontology:
Molecular function: structural constituent of ribosome
Cellular component: ribosome
Homologues: Paralogues in human: RNA5S1 (100% identical), RNA5S10 (100% identical), RNA5S11 (100% identical), RNA5S12 (100% identical), RNA5S13 (100% identical), RNA5S14 (100% identical), RNA5S15 (100% identical), RNA5S16 (100% identical), RNA5S17 (100% identical), RNA5S3 (100% identical), RNA5S4 (100% identical), RNA5S5 (100% identical), and 26 more.